TM4SF1 (transmembrane 4 L six family member 1)
Diseases named in the same sentence as TM4SF1 in open-access papers (continued):
Sharing a sentence is not in itself a finding about the gene and the disease.
cancer (continued). "The relevant mechanisms underlying the involvement of TM4SF1 in cancer cell invasion and metastasis are still not clear." (PMID 30876464, 2019). "TM4SF18 is highly homologous to TM4SF1 but has yet to be studied in any aspect of cancer biology." (PMID 30897168, 2019). "Therefore, the role of TM4SF1 expression as a prognostic marker is dependent on the types of cancers." (PMID 29665316, 2018). "It seems that the role of TM4SF1 in cancer progression and invasion is also tissue‐specific." (PMID 29665316, 2018). "One gene involved in free radical scavenging, SOD3, was downregulated, whereas the genes associated with cell cycle or cancer, including GADD45B, ID1, KLF10, CSRNP1, and TM4SF1, were upregulated in F. nucleatum-infected GF(P22) cells when compared to F. nucleatum-infected GF(P4) cells." (PMID 29190775, 2017). "The data presented here, coupled with those from our earlier report, demonstrate TM4SF1 and miR-141 could be a potential marker of cancer stem-like cells of ESCC." (PMID 27974706, 2017). "In this study, we investigated the role of TM4SF1 and miR-141 in cancer stem-like cells." (PMID 27974706, 2017). "Also, TM4SF1 is defined as a cancer stem cell marker, and TM4SF1 and TM4SF5 are reported to be involved in epithelial-to-mesenchymal transition, which is also associated with stemness properties." (PMID 25344917, 2014). "To causally determine whether TM4SF1 palmitoylation is required for the palmitate-induced phosphorylation of STAT3, we overexpressed wildtype and palmitoylation mutated (C79A+C88A) Tm4sf1 in 4T1 cancer cells silenced for wildtype Tm4sf1." (PMID 41826695, 2026). "Therefore, we detected using protein mass spectrometry the genes whose expression changed with the silencing of TM4SF1, and screened out some genes with significant correlation with the cancer stem–related molecules and NOTCH pathway molecules via the correlation analysis of the GEPIA database." (PMID 37069693, 2023). "Based on the current finding, TM4SF1 could bring new insights into its impact on cancer metastasis." (PMID 36678607, 2023). "However, few reports exist on the relationship between TM4SF1 and cancer stemness." (PMID 37069693, 2023). "Hence, we hypothesized that TM4SF1 might affect the cancer stemness of HCC cells by regulating MYH9 and activating the NOTCH pathway." (PMID 37069693, 2023). "Interestingly, TM4SF1 + cancer cells were found in AIS, MIA and IAC." (PMID 36434043, 2022). "However, T classification, one of the cancer malignancy risk factors, showed no significant relation with TM4SF1 expression statistically, further study are needed by expanding the sample size." (PMID 35835740, 2022). "In addition, TM4SF1 is recruited by and binds to TERMs through its intracellular domains, where it associates with other tetraspanins, such as CD63 and CD82, and thus influences the pro-migratory activity of cancer cells." (PMID 33015133, 2020). "Here, we review the diverse functions of TM4SF1 in numerous malignancies, with an aim to fully understand the interaction between the expression of this transmembrane protein and the biological behaviors of cancer and to provide a basis for exploring new therapeutic targets." (PMID 33015133, 2020). "However, the exact role of TM4SF1 in cancer remains controversial." (PMID 33015133, 2020). "Overall, these data indicated that TM4SF1 may be a potential prognostic marker for predicting metastasis and a target for individualized drug therapy, which may prevent tumour metastasis and improve the prognosis of cancer patients." (PMID 33153498, 2020). "Thus, inhibition of TM4SF1 expression may be a useful strategy to inhibit tumor growth and to reduce the migration and invasion of cancer cells." (PMID 27153056, 2016).
cancer (continued). "In addition, when cancer cells with TM4SF1 overexpression were injected into nude mice, this increased the expression of genes related to angiogenesis (uPA, MMP-2, MMP-9 and VEGF), decreased the expression of TIMP (an inhibitor of MMP), and led to promotion of angiogenesis and tumor growth." (PMID 27153056, 2016). "TM4SF1 may promote the invasion and metastasis of cancers through one or more mechanisms." (PMID 27153056, 2016). "In line, we further observed that silencing Zdhhc20 decreased the plasma membrane localization of TM4SF1 in 4T1 and EMT6.5 cancer cells based on immunofluorescence." (PMID 41826695, 2026). "Specifically, we injected Zdhhc20 silenced, Tm4sf1 palmitoylation mutant (C79A+C88A) expressing and control EMT6.5 and/or 4T1 cancer cells into the mammary fat pad and/or intravenously to mice." (PMID 41826695, 2026). "HDAC6 is upregulated in various cancer types and promotes cancer cell metastasis, suggesting a potential connection between HDAC6 and TM4SF1 in tumor cells." (PMID 41226530, 2025). "Meanwhile, the anti-TM4SF1 antibody decreased the level of phosphorylated PKCα, and also reduced DNM2 levels in cancer patients' platelets, but had little effect on total PKCα levels." (PMID 39113702, 2024). "We performed detailed analysis of gene expression profiles in mouse Tm4sf1+ cells, including BsP and TPCS, across normal tissue, injured tissue, and cancer." (PMID 38582099, 2024). "Expression Atlas revealed that TM4SF1, TM4SF4, TM4SF18, and TM4SF19 were expressed in various cancer cell lines." (PMID 38206300, 2024). "Accumulating evidence has demonstrated, among six TM4SF members, the regulatory roles of transmembrane 4 L6 domain family members, particularly TM4SF1, TM4SF4, and TM4SF5, in cancer angiogenesis, progression, and chemoresistance." (PMID 36678607, 2023). "After protein mass spectrometry analysis of TM4SF1, we screened out the downstream protein MYH9, which, as a widely expressed cytoskeletal protein, was closely related to a variety of cancers." (PMID 37069693, 2023). "In order to prove the correlation between TM4SF1 and cancer stemness, we used OCLR algorithm to evaluate the stemness index of TM4SF1 based on the tissues of 371 patients with HCC in TCGA database." (PMID 37069693, 2023). "For example, spots enriched with TM4SF1, PRSS1/2, and SERPINA1 are also predicted to, respectively, have high proportions of Cancer clone A cells, Acinar cells, and Ductal centroacinar cells." (PMID 37550279, 2023). "As compared to others, this review aimed to present a focused insight and update on the biological roles of TM4SF1, TM4SF4, and TM4SF5 in the progression, metastasis, and chemoresistance of various cancers." (PMID 36678607, 2023). "TM4SF1 promoted epithelial–mesenchymal transition (EMT) and cancer stemness via the Wnt/β-catenin/SOX2 pathway in CRC, which revealed that TM4SF1 modulated SOX2 expression in a Wnt/β-catenin activation-dependent manner." (PMID 36766788, 2023). "Using the gene set enrichment analysis (GSEA) technology, we enriched the signaling pathways significantly related to TM4SF1 and found that the NOTCH pathway was related to cancer stemness." (PMID 37069693, 2023). "Compared to TM4SF1, relatively fewer studies have investigated the regulatory roles of TM4SF4 in cancer." (PMID 36678607, 2023). "The findings also showed that the mRNA expression levels of TM4SF1, FASN, and IMPDH1 were higher in cancer tissues, whereas the mRNA expression of KCNJ15 was higher in normal tissues." (PMID 35480865, 2022). "Thus, the role of TM4SF1 in cancer progression and invasion may also be tissue-specific." (PMID 35153775, 2022). "The expression of MUC1 was positively correlated with cancer stem cell markers such as CD24, PSCA and TM4SF1, which indicated that the high expression of MUC1 in malignant cells was associated with tumor proliferation." (PMID 36104333, 2022).
cancer (continued). "TM4SF1, a member of the TM4SF protein family, is identified as an oncogene and regulates proliferation, metastasis, and invasion in various cancers, including CRC55." (PMID 33958586, 2021). "A recent study revealed that TM4SF1 overexpression increases the expression of SOX2 and NANOG, sustains the manifestation of cancer stem cell traits, and drives metastatic reactivation in the lung and brain." (PMID 33153498, 2020). "Mechanistically, we found that TM4SF1 promotes cell metastasis and maintains the phenotypes of EMT and cancer stemness via the Wnt/β-catenin/c-Myc/SOX2 pathway in CRC." (PMID 33153498, 2020). "A series of in vitro and in vivo experiments were conducted to reveal the mechanisms by which TM4SF1 modulates EMT and cancer stemness in CRC." (PMID 33153498, 2020). "The effect of TM4SF1 on the epithelial-to-mesenchymal transition (EMT) and cancer stemness of CRC cells was investigated by Transwell, wound healing and sphere formation assays." (PMID 33153498, 2020). "Of these, ALDH1A3, TM4SF1, and PROM1 were identified as cancer stem cell markers and CAV1 was EMT‐related." (PMID 31498560, 2019). "Thus, our results provide compelling evidence that miR-141 and TM4SF1 could be a potential target of the eliminating cancer stem-like cells in ESCC and might promote the development of new therapeutic strategies and efficient drugs to target ESCC stem-like cells." (PMID 27974706, 2017). "STAB1, TM4SF1, and TNS3 are involved in cell adhesion and motility, which are relevant to cancer metastasis and invasion, however, their roles in interaction between leukemic stem cells and bone marrow niche deserve further investigation." (PMID 26517675, 2015). "TM4SF1 and TM4SF5 affect migratory mechanisms crucial to cancer invasion and metastasis, making them as crucial targets for cancer therapy." (PMID 25344917, 2014). "This is partially similar to TPCS in human cancer which overexpressed CD44 and TM4SF1." (PMID 38582099, 2024). "The study confirmed that TM4SF1 could regulate the NOTCH pathway by upregulating MYH9, thus promoting cancer stemness and Lenvatinib resistance in HCC." (PMID 37069693, 2023). "Hence, TM4SF1, TM4SF4, and TM4SF5 are promising therapeutic targets for different cancer types preclinically and deserve further investigation." (PMID 36678607, 2023). "We verified that TM4SF1 could activate the NOTCH signaling pathway by positively regulating MYH9, which ultimately promoted the cancer stemness in HCC and enhanced the drug resistance of HCC cells to Lenvatinib." (PMID 37069693, 2023). "Like TM4SF1, the expression profile of TM4SF5 has been studied and highly expressed in many cancers, such as pancreatic, gastric, colon, liver, papilla vateri, soft tissue, non-endocrine lung, and adrenocorticotropic hormone (ACTH)-negative bronchial carcinoid." (PMID 36678607, 2023). "TM4SF1 also appears to be broadly involved in the cancer-to-mesothelial cell attachment process independent of histology." (PMID 32780245, 2020). "Additionally, cancer stem cell markers were also overexpressed in N1b PTMC (ALDH1A3: 4.9‐fold, TM4SF1: 7.6‐fold, and PROM1: 5.4‐fold) (all P < .001)." (PMID 31498560, 2019). "Silencing of TM4SF1 appears to restore the balance between MMP and TIMP, increase the inhibition of MMP by TIMP, reduce degradation of the ECM, thus inhibiting the invasion and metastasis of cancer cells." (PMID 27153056, 2016). "We speculate that TM4SF1-mediated upregulation of uPA, MMP-2, and MMP-9 increases the degradation of ECM by cancer cells, leading to invasion and metastasis of cancer cells." (PMID 27153056, 2016). "Silencing of TM4SF1 also increases the expression of TIMP (an inhibitor of MMP), inhibits the expression of pro-angiogenic genes (uPA, MMP-2, MMP-9, and VEGF) and suppresses the proliferation, invasion and metastasis of cancer cells." (PMID 27153056, 2016).
cancer (continued). "XAGE-1, COL4A1, S100P and TM4SF1 were observed to show elevated expression in various cancers, but the expression level of these genes in HCC has not been reported previously." (PMID 19171046, 2009). "We suggest that the up-regulations of the genes AKR1C1/C2, TM4SF1 and NR0B1 in SP of human adenocarcinoma A549 cells could be a target of poor prognosis in anti-cancer therapy." (PMID 18034892, 2007). "Therefore, we hypothesized that TM4SF1 activated the NOTCH pathway by positively regulating MYH9, which in turn promoted cancer stemness in HCC." (PMID 37069693, 2023). "We hypothesized that TM4SF1 might promote cancer stemness in HCC via activating the NOTCH signaling pathway." (PMID 37069693, 2023). "Volcano plot showed significantly upregulated transcripts of transmembrane 4 L6 family member 1 (TM4SF1), neuritin 1 (NRN1), MT2, mucin‐like protein 3 (MUCL3), complement component 4B (C4B) and insulin‐like growth factor‐binding protein 4 (IGFBP4) genes in treated KPC mice cancer cells." (PMID 38131168, 2023). "After verifying the promoting effect of TM4SF1 on the cancer stemness of HCC, we speculated based on the close relationship between cancer stemness and tumor drug resistance, that TM4SF1 could enhance the Lenvatinib resistance in HCC cells by promoting the cancer stemness in HCC." (PMID 37069693, 2023). "Therefore, enrichment of AKR1C1/C2, TM4SF1 and NR0B1 in SP of A549 cells might be a target of poor prognosis in cancer therapy." (PMID 18034892, 2007). "Moreover, mutating the C79A+C88A palmitoylation sites of TM4SF1 in 4T1 cancer cells decreased metastatic burden of mice compared to control cells expressing wildtype TM4SF1 regardless of whether the cells were injected intravenously or in the mammary fat pad." (PMID 41826695, 2026). "However, TM4SF1 did not affect cancer cell proliferation, as examined in vitro and in vivo studies." (PMID 36678607, 2023). "Interestingly, the tetraspanin TM4SF1 was found to be required for collagen-induced DDR1 clustering in cancer cells, but this clustering process did not result in DDR1 autophosphorylation, and instead led to non-canonical DDR1 signalling, independent of its kinase activity." (PMID 31745115, 2019). "Taken together, we can come to the conclusion that TM4SF1 could be a candidate surface protein marker that could discriminate cancer stem-like cells from ESCC cells, and could promote the ability to self-renew by increasing the number of cancer stem-like cells." (PMID 27974706, 2017).
tumor (71 papers, 2006 to 2026). "The expression of TM4SF1 in tumor-associated endothelial cells and its close relationship with microvascular invasion have not been fully investigated." (PMID 40123905, 2025). "We checked the associations within each TM4SF1-expressing tumor in our scRNA-seq dataset and found these genes to be positively correlated with TM4SF1 expression and statistically significant in each case." (PMID 40527915, 2025). "Single cell analysis of histologic variant bladder tumors detects a shared CA125+ tumor cell state associated with aggressive clinical features and reveals enriched expression of TM4SF1, a membrane protein that can be targeted with CAR T cells." (PMID 40527915, 2025). "TM4SF1 was known to be a tumor cell‐associated antigen expressed at low levels in normal vascular endothelium." (PMID 38946725, 2024). "The expression of TM4SF1, tumor size, and Edmondson-Steiner grade were found to be linked with the overall survival percentage of 90 HCC patients in both univariate and multivariate analyses." (PMID 37069693, 2023). "The bulk expression of CSTB and TM4SF1 was associated with both advanced tumor stage and poor PFS time in CRC patients." (PMID 36816947, 2023). "TM4SF1 was initially defined as a tumour-associated antigen that shares certain tetraspanin functions, including stabilization of cell signalling complexes and roles in cell proliferation, adhesion, and motility." (PMID 33153498, 2020). "TM4SF1 is also associated with pathologic angiogenesis, targeting TM4SF1 would provide a dual anticancer mechanism: simultaneously targeting tumor cells and the tumor vasculature (secondary mechanism)." (PMID 31140150, 2019). "Low expression of miR-206 in cancerous tissue is linked to poor overall survival of patients The anti-tumor effect of miR-206 in CRC is mediated via targeting various genes such as transmembrane 4 L6 family member 1 (TM4SF1) and VEGF." (PMID 31887997, 2019). "Transmembrane‐4‐L‐six‐family member‐1 (TM4SF1), a tumor‐associated antigen, is overexpressed in most epithelial cell carcinomas and a potential target for antibody‐mediated therapy." (PMID 29665316, 2018). "To determine the molecular mechanism of how TM4SF1 regulates tumor growth, we focused on the cell apoptosis; it is well known that decreased susceptibility to apoptosis plays an important role in tumor growth." (PMID 27153056, 2016). "Among the genes represented in the Met library, many are associated to tumor growth, invasiveness and metastasis, such as TM4SF1, LAMA4, G3BP2, CD59 antigen, and SPP1." (PMID 18211678, 2008). "TM4SF1 was reported as a tumor-associated antigen recognized by the antibody L6 in 1986." (PMID 41226530, 2025). "Although various factors like ABC family of transporters, regulators like TM4SF1, various cofactors had been implicated in drug resistance associated with PDACs, none of these were able to distinctly classify them to particular tumor grade." (PMID 31622355, 2019). "In addition, the positive expression of TM4SF1 protein in tissues in all metastatic lymph node foci and the matched primary loci indicated that TM4SF1 protein might be closely associated with tumor invasion and metastasis." (PMID 30876464, 2019). "Using the CCK-8 assay, colony formation assay, wound healing assay, Transwell assay, and subcutaneous tumor xenograft models, the function of TM4SF1 in tumor growth was evaluated in vivo and in vitro." (PMID 42305440, 2026). "Why is TM4SF1 expression restricted to endothelial and mesenchymal stem cells among normal cell types, but ubiquitous among the tumor cells of solid cancers?" (PMID 41226530, 2025). "More importantly, SecTA expresses multiple molecules related to cell migration and adhesion, such as CEACAM6 and TM4SF1, which not only increase tumour cell invasiveness but also create conditions for distant metastasis." (PMID 40539065, 2025).